SQLE (squalene epoxidase)
Diseases named in the same sentence as SQLE in open-access papers (continued):
Sharing a sentence is not in itself a finding about the gene and the disease.
colon cancer (3 papers, 2013 to 2022). "The two cohorts' top 100 differentially expressed genes (based on survival status) were compared, revealing that ANO1 and SQLE are the two genes commonly differentially expressed between those TAZ-AXL-CTGF-high colon cancer patients who are still alive and those who are deceased." (PMID 23372686, 2013). "We examined the expression of several key cholesterol biosynthetic enzymes (HMGCR, FDPS, and SQLE) in paired colon tumor and non-tumor tissues performed by western blot and immunohistochemistry analysis." (PMID 34621019, 2021). "Importantly, we also identified two potential therapeutic targets, ANO1 and SQLE, for patients with upregulated TAZ-AXL-CTGF expression; downregulation of either of these two genes may greatly improve the survival of TAZ-AXL-CTGF-high colon cancer patients." (PMID 23372686, 2013).
esophageal squamous cell carcinoma (3 papers, 2021 to 2025). Esophageal squamous cell carcinoma (ESCC) is a type of esophageal carcinoma (EC) that can affect any part of the esophagus, but is usually located in the upper or middle third. "In esophageal squamous cell carcinoma (ESCC), SQLE, as a downstream target gene of miR-133b, can induce epithelial-to-mesenchymal transition (EMT) to promoting tumor metastasis." (PMID 34715817, 2021). "SQLE (squalene epoxidase), commonly known as a key enzyme of cholesterol synthesis, can also induce EMT (epithelial-to-mesenchymal transition) via regulating miR-133b in esophageal squamous cell carcinoma." (PMID 33672990, 2021). "In esophageal squamous cell carcinoma (ESCC), LPCAT1 regulates the upregulation of the cholesterol synthesis enzyme SQLE by promoting PI3K activation." (PMID 40145543, 2025).
glioma (3 papers, 2017 to 2024). A benign or malignant brain and spinal cord tumor that arises from glial cells (astrocytes, oligodendrocytes, ependymal cells). "In GBM, SQLE was identified to be lowly expressed in temozolomide-resistant glioma cells and involved in the ERK-mediated temozolomide resistance of glioma cells, while overexpression of SQLE significantly inhibited the migration and invasion of tumor cells." (PMID 38612682, 2024). "Genes in the mevalonate pathway (ACAT2, HMGCS1, and HMGCR) and downstream in the cholesterol biosynthetic pathway (FDPS, FDFT1, and SQLE), were all downregulated in dense NHAs but not dense glioma TS lines." (PMID 28118603, 2017).
non-small cell lung carcinoma (3 papers, 2022 to 2024). A group of at least three distinct histological types of lung cancer, including non-small cell squamous cell carcinoma, adenocarcinoma, and large cell carcinoma. "Squalene epoxidase (SQLE), as a rate-limiting enzyme in cholesterol biosynthesis, is associated with poor prognosis in non-small cell lung cancer patients due to its role in shaping the immune-cold phenotype." (PMID 38665847, 2024). "Analysis of data from the Cancer Cell Line Encyclopedia (CCLE) revealed that the expression levels of HMGCS1, HMGCR, IDI1, FDFT1, and SQLE were significantly higher in SCLC cell lines compared to non-small cell lung cancer (NSCLC) cell lines and other cancer cell lines." (PMID 39669201, 2024).
nonalcoholic fatty liver disease (3 papers, 2019 to 2025). "CA3 was also found to interact with squalene epoxidase (SQLE), a key enzyme implicated in non-alcoholic steatohepatitis—an advanced and inflammatory form of non-alcoholic fatty liver disease characterized by hepatocyte injury, inflammation, and fibrosis." (PMID 41465490, 2025).
osteosarcoma (3 papers, 2024 to 2025). A usually aggressive malignant bone-forming mesenchymal neoplasm, predominantly affecting adolescents and young adults. "Further investigation into the regulatory mechanisms of risk genes, such as EDIL3 and SQLE, revealed that these genes are potential candidates for therapeutic targeting, as indicated by their significant role in the progression and prognosis of osteosarcoma." (PMID 39015570, 2024). "Knockdown of three of these genes—CLTCL1, EDIL3, and SQLE—resulted in substantial changes in proliferation rate, migration capacity, and apoptosis rate of osteosarcoma cells." (PMID 39015570, 2024). "MLH1 was downregulated in osteosarcoma samples, potentially indicating a tumor suppressive function, whereas SQLE was upregulated, suggesting a role in tumor progression." (PMID 39015570, 2024). "In osteosarcoma cells, both the mRNA and protein expression levels of SQLE and EDIL3 genes show significant elevation." (PMID 39015570, 2024). "PCR analysis showed increased mRNA levels of the genes FDX1 and SQLE in osteosarcoma tissues." (PMID 38546286, 2025). "The expression patterns of MLH1 and SQLE suggest differential roles in osteosarcoma pathology." (PMID 39015570, 2024). "The experimental results align with the conclusions of previous studies, suggesting that MLH1 and SQLE genes could serve as biomarkers for osteosarcoma prognosis and therapeutic targets." (PMID 39015570, 2024). "However, mRNA expression levels of EDIL3 and SQLE genes were markedly higher in osteosarcoma cell lines compared to MSCs." (PMID 39015570, 2024). "In recent years, the roles of MLH1 and SQLE genes in osteosarcoma have garnered attention." (PMID 39015570, 2024). "According to all experimental results, CLTCL1, MTM1, and MLH1 are likely tumor suppressor genes exerting inhibitory effects on osteosarcoma development, while SQLE and EDIL3 may function as targets promoting tumor proliferation, thus presenting new therapeutic potential." (PMID 39015570, 2024). "Additionally, when compared to MSC cell lines, human osteosarcoma cell lines showed significantly higher protein expression levels of SQLE and EDIL3, whereas CLTCL1 demonstrated significantly higher protein expression levels in MSC cell lines than in human osteosarcoma cell lines." (PMID 39015570, 2024). "The hFOB 1.19 and MG‐63 cells were utilized to validate the mRNA expression of SQLE and FDX1 in osteosarcoma (OS)." (PMID 38546286, 2025). "On the other hand, the expression levels of SQLE and EDIL3 genes were considerably higher in osteosarcoma samples compared to the adjacent normal tissues (P=0.033 and P=0.026, respectively)." (PMID 39015570, 2024). "Knockdown of SQLE and EDIL3 gene expression in osteosarcoma cells resulted in a significant decrease in proliferation and migration abilities, accompanied by a notable increase in apoptosis rate." (PMID 39015570, 2024).
tinea (3 papers, 2020 to 2024). "In vitro studies have shown that point mutations in the squalene epoxidase gene can lead to terbinafine resistance, resulting in difficult-to-treat tinea corporis, tinea cruris, and tinea faciei." (PMID 38667966, 2024). "Terbinafine, a synthetic allylamine derivative that inhibits fungal growth by blocking the activity of squalene epoxidase (SQLE) resulting in the accumulation of squalene and depletion of ergosterol from the fungal wall, is considered as the first-line therapy for tinea infections." (PMID 34072049, 2021).
liver cancer (2 papers, 2023). An epithelial or non-epithelial malignant neoplasm that arises from the liver. "Several enzymes such as SREBP2, HMGCR, SQS, OSC, and SQLE which are involved in cholesterol synthesis are significantly upregulated in liver cancer mouse model." (PMID 37089950, 2023).
lymphoma (2 papers, 2022 to 2023). A malignant (clonal) proliferation of B- lymphocytes or T- lymphocytes which involves the lymph nodes, bone marrow and/or extranodal sites. "On the other hand, the dependence on extracellular cholesterol in tumors with loss of squalene monooxygenase (SQLE) was demonstrated in lymphoma." (PMID 35286311, 2022). "Squalene epoxidase (SQLE), the rate-limiting enzyme in cholesterol biosynthesis, may play a role in ferroptosis because squalene accumulation in cholesterol auxotrophic lymphomas caused by SQLE loss suppressed ferroptosis." (PMID 37612411, 2023).
sarcoma (2 papers, 2024). A usually aggressive malignant neoplasm of the soft tissue or bone. "In this study, we aimed to investigate the prognostic value of squalene epoxidase (SQLE) as a biomarker in sarcoma and explore its correlation with immune cell infiltration, focusing on the role of Th2 cells, DCs, and pDCs." (PMID 38335381, 2024). "Several studies have revealed that SQLE is over-expressed in various tumors, acting as an oncogene; however, its function in sarcoma remains uncertain." (PMID 38338920, 2024). "In our study, SQLE knock-down suppressed proliferation and induced the apoptosis of sarcoma cells, strengthening the notion that SQLE has a targetable oncogenic function in sarcoma." (PMID 38338920, 2024). "In conclusion, our study found that the expression of SQLE was significantly upregulated and closely related to the poor prognosis of sarcoma patients." (PMID 38335381, 2024). "Notably, SQLE, a rate-limiting enzyme in cholesterol biosynthesis, was identified as a potential therapeutic target for sarcoma." (PMID 38338920, 2024). "Furthermore, silencing SQLE substantially inhibited cell proliferation and colony formation but promoted the apoptosis of sarcoma cells, confirming that SQLE is an oncogenic protein." (PMID 38338920, 2024).
arteriosclerosis (1 paper, 2020). A vascular disorder characterized by thickening and hardening of the walls of the arteries. "Presence of arteriosclerosis associated significantly with expression of SQLE, FDPS, MVD, HMGCS1, HSD17B7 and HSF1 (all p≤0.05)." (PMID 32353828, 2020).
cholesterol metabolism disorders (1 paper, 2024). "Disruption of SQLE function is linked to cholesterol metabolism disorders and has been implicated in various diseases, including MASLD." (PMID 38952069, 2024).
cutaneous sarcoidosis (1 paper, 2024).
developmental disability (1 paper, 2022). Disorders in which there is a delay in development based on that expected for a given age level or stage of development. "SQLE has been linked to Rett syndrome pathogenesis, and mutations in DHCR7 result in a developmental disability known as Smith-Lemli-Lopiz Syndrome (SLOS, MIM 270400), which resembles SMS in some aspects." (PMID 36411275, 2022).
gastric cancer (1 paper, 2025). A primary or metastatic malignant neoplasm involving the stomach. "Transcriptome sequencing data revealed a substantial increase in squalene epoxidase (SQLE) expression in CagA-positive gastric cancer cells." (PMID 39809787, 2025). "Within this pathway, the roles of farnesyl diphosphate synthase (FDPS), isopentenyl-diphosphate delta isomerase 1 (IDI1), and SQLE in gastric cancer remain largely unexplored." (PMID 39809787, 2025). "Further investigation uncovered that CagA transcriptionally upregulates SQLE, a crucial enzyme in cholesterol metabolism, leading to elevated cholesterol levels in gastric cancer cells." (PMID 39809787, 2025). "qPCR and WB assays demonstrated that gastric cancer cells co-cultured with CagA-positive H. pylori strains exhibited elevated expression of SQLE." (PMID 39809787, 2025). "CCK-8 assays demonstrated that the overexpression of CagA and SQLE could enhance gastric cancer cell proliferation." (PMID 39809787, 2025).
hepatoblastoma (1 paper, 2025). Hepatoblastoma (HB) is a malignant hepatic tumor and is the most common pediatric liver cancer. "Hepatoblastoma exhibited significantly higher levels of cholesterol synthase (SREBF2, SQLE, HMGCS1) compared to normal liver tissues, which indicated higher metabolic activity." (PMID 40271711, 2025).
Hyperkeratosis (1 paper, 2022). Hyperkeratosis is a histopathological term defining a thickened stratum corneum and may be present in many different skin conditions, with many possible overlaps. "Patients with hyperkeratosis and parakeratosis, acanthosis thickening had increased expression of 13 the same genes, including SQLE, STRN, EIF4E, and MYO1B." (PMID 35277199, 2022). "Therefore, we speculate that AP-1 upregulates the expression of SQLE, STRN, EIF4E, and MYO1B; it brings keratinocytes EMT, which further mediates hyperkeratosis with parakeratosis and acanthosis thickening." (PMID 35277199, 2022).
metastatic prostate carcinoma (1 paper, 2025). A carcinoma that arises from the prostate gland and has spread to other anatomic sites. "Eight genes (CYC, CYP51A1, DHFR, EBP, KIF15, PPM1D, SQLE, and UMPS) demonstrated strong dependency in cell lines and were also associated with worse prognosis clinically, representing potential therapeutic targets in metastatic prostate cancer." (PMID 40405591, 2025). "The eight genes where higher expression was associated with worse prognosis (CYC, CYP51A1, DHFR, EBP, KIF15, PPM1D, SQLE, and UMPS) represent potential additional therapeutic targets in metastatic prostate cancer." (PMID 40405591, 2025).
Neonatal sepsis (1 paper, 2020). Systemic inflammatory response to infection in newborn babies.
neuroblastoma (1 paper, 2025). Neuroblastoma (NB) is the most common solid, extracranial childhood tumor. "Interestingly, we also observed nuclear translocation of SQLE in neuroblastoma cells, a phenomenon not previously reported." (PMID 40513779, 2025). "Interestingly, we also detected the nuclear translocation of SQLE in neuroblastoma cells, a phenomenon not previously reported." (PMID 40513779, 2025).
neuroendocrine tumors (1 paper, 2019). "We conducted a chemical biology screen and identified a subset of neuroendocrine tumors displaying a striking pattern of sensitivity to inhibition of the cholesterol biosynthetic pathway enzyme squalene epoxidase (SQLE)." (PMID 30626880, 2019).
Niemann-Pick disease, type C2 (1 paper, 2017). Niemann-Pick disease type C2 is a rare metabolic condition that affects many different parts of the body. "In the larval exposure, we also detected increased expression of hdmh, erg1, cp51a, and npc2 (encoding the proteins squalene epoxidase, and cytochrome P450 51A, Niemann-Pick disease, type C2, respectively) at the latest stages examined (14 and 18 dph)." (PMID 28117666, 2017).
Obesity (1 paper, 2024). Accumulation of substantial excess body fat. "Interestingly, weight loss induces remodeling of cholesterol metabolism pathways in monocytes, including the downregulation of SQLE expression, suggesting that SQLE may be a potential therapeutic target for obesity-associated T2DM." (PMID 39588004, 2024). "SQLE is not only widely expressed in various tissues and organs but also participates in the onset and progression of numerous metabolism-related diseases, such as NAFLD, cancer, DM, and obesity." (PMID 39588004, 2024).
onychomycosis (1 paper, 2025). "An additional challenge is the growing prevalence of terbinafine resistance, commonly associated with mutations in the squalene epoxidase (SQLE) gene, prompting consideration of alternative therapies for recalcitrant onychomycosis." (PMID 41156660, 2025).
ovarian hypofunction (1 paper, 2023). "SQLE may be a regulatory gene related to steroid biosynthesis and inflammation, and it can reflect the changes in granulosa cells in patients with ovarian hypofunction." (PMID 37560165, 2023).
psoriasis (1 paper, 2022). An autoimmune condition characterized by red, well-delineated plaques with silvery scales that are usually on the extensor surfaces and scalp. "In this regard, it is interesting to note that AP-1 upregulates the gene expression of SQLE, STRN, EIF4E, and MYO1B might to promote the abnormality of keratinocytes and immune system to mediate the occurrence of psoriasis." (PMID 35277199, 2022).
squamous cell lung carcinoma (1 paper, 2021). A carcinoma arising from squamous bronchial epithelial cells. "In squamous cell lung carcinoma (SCLC), the expression of SQLE was significantly higher in tumor tissues than that in pericarcinoma tissues, and overexpression of SQLE was closely related to poor clinical stages and lymphatic metastasis." (PMID 34715817, 2021).
stomach adenocarcinoma (1 paper, 2025). "The circRNA–cholesterol axis extends to gastric malignancies, where circ_0000182 promotes sterol overproduction in stomach adenocarcinoma (STAD) by sponging miR-579-3p to derepress SQLE, a rate-limiting enzyme in cholesterol biosynthesis." (PMID 40722703, 2025).
thyroid cancer (1 paper, 2021). "Meanwhile, AKR1C1, HMGCR, TFRC, SQLE, and PGD were risk factors for thyroid cancer prognosis." (PMID 33928101, 2021). "Our data suggested that AKR1C1 (p < 0.0001), DPP4 (p < 0.0001), GPX4 (p = 0.0001), GSS (p < 0.0001), HMGCR (p < 0.0001), TFRC (p < 0.0001), SQLE (p = 0.0004), and PGD (p = 0.0005) were all significantly highly expressed in thyroid cancer tissues compared to normal tissues." (PMID 33928101, 2021).
tinea capitis (1 paper, 2020). "The five strains of T. mentagrophytes characterised in this paper were screened for the squalene epoxidase (SQLE) mutation as it has been demonstrated that zoophilic strains of T. mentagrophytes could present some resistance to terbinafine, which is the main treatment of tinea capitis in Belgium." (PMID 33003309, 2020).